HEPHL1 (hephaestin like 1)
Description:
Is a copper-binding glycoprotein with ferroxidase activity. It oxidizes Fe(2+) to Fe(3+) without releasing radical oxygen species. May be involved in the regulation of intracellular iron content.
Synonyms: DKFZp686F22190; Zp; HJDD
Tractability: Antibody: UniProt predicts a signal peptide or a membrane-spanning region; its Gene Ontology location is reachable by antibodies, with medium confidence. PROTAC: ubiquitination databases record sites on it.
Gene: Protein-coding gene on chromosome 11 (94,021,354 to 94,114,208, forward strand). Ensembl gene ENSG00000181333.
Subcellular location: Membrane
Gene Ontology:
Molecular function: ferroxidase activity; copper ion binding; oxidoreductase activity
Biological process: intracellular iron ion homeostasis
Cellular component: plasma membrane; membrane
Genetic constraint (gnomAD): Loss-of-function variants: 101 observed, 104.05 expected, observed/expected ratio (o/e) 0.97, 90% interval 0.82 to 1.14. The upper end of that interval is the gene's LOEUF score, 1.14, which puts it in group 5 of 6, group 1 being the genes least tolerant of losing a copy. Missense variants: 1,259 observed, 1,270.4 expected, observed/expected ratio (o/e) 0.99, 90% interval 0.94 to 1.04. Synonymous variants: 456 observed, 466.5 expected, observed/expected ratio (o/e) 0.98, 90% interval 0.9 to 1.06.
Gene-disease validity (ClinGen):
ClinGen rates the evidence that HEPHL1 causes each of these diseases.
pili torti-developmental delay-neurological abnormalities syndrome (autosomal recessive): Limited. Pili torti-developmental delay-neurological abnormalities syndrome is characterized by growth and developmental delay, mild to moderate neurologic abnormalities, and pili torti.
Homologues: Orthologues: chimpanzee HEPHL1 (99% identical), macaque HEPHL1 (97% identical), dog HEPHL1 (90% identical), pig HEPHL1 (90% identical), rabbit HEPHL1 (90% identical), guinea pig HEPHL1 (90% identical), rat Hephl1 (88% identical), mouse Hephl1 (87% identical), zebrafish f8 (33% identical). Paralogues in human: HEPH (49% identical), CP (47% identical), F8 (35% identical), F5 (33% identical), CNTNAP5 (16% identical), CNTNAP3 (15% identical), CNTNAP4 (15% identical), CNTNAP3B (15% identical), CNTNAP2 (14% identical), CUBN (14% identical), NRXN2 (13% identical), CNTNAP1 (13% identical), and 23 more.
Diseases named in the same sentence as HEPHL1 in open-access papers:
HEPHL1 is named in the same sentence as 19 diseases in open-access papers, as found by Europe PMC text mining. Sharing a sentence is not in itself a finding about the gene and the disease. The quoted sentences say what the papers report.
cognitive delays (2 papers, 2019 to 2021). "In humans, recessively inherited biallelic HEPHL1 variants are associated with a phenotype characterized by abnormal hair (pili torti and trichorrhexis nodosa), joint laxity, severe heat intolerance, and developmental delay (OMIM 261990)." (PMID 33926013, 2021). "We do not know if our patient’s mild cognitive delays, heat intolerance, and chronic leg pain are related to the HEPHL1 mutations." (PMID 31125343, 2019).
COVID-19 (2 papers, 2021 to 2025). A disease caused by infection with severe acute respiratory syndrome coronavirus 2. "Novel transcriptional signatures of the SARS-CoV-2 virus, including PGLYRP4 and HEPHL1, were detected, and their prospective mechanisms in the pathogenesis of COVID-19 and associated complications were suggested." (PMID 34441862, 2021). "Examining hub genes, like PGLYRP4 and HEPHL1, that have been connected to COVID-19 may shed light on how colistin affects the immune system." (PMID 40428842, 2025). "The novel hub gene signature that was detected in our study, including PGLYRP4 and HEPHL1, may shed light on the pathogenesis of COVID-19, holding promise for future prognostic and therapeutic approaches." (PMID 34441862, 2021).
hypotrichosis (2 papers, 2019 to 2021). A congenital condition, usually due to genetic aberrations, that is characterized by a lack of hair growth on the head and/or body. "We also note that Belted Galloway cattle with homozygous loss-of-function mutations in HEPHL1 have hypotrichosis, and our Hephl1 knockout mouse exhibits curly whiskers resembling pili torti." (PMID 31125343, 2019). "This rare recessive HEPHL1-related form of hypotrichosis provides a novel large animal model for similar human conditions." (PMID 33926013, 2021).
actinic keratosis (1 paper, 2023). A precancerous lesion of the skin composed of atypical keratinocytes. "Five new genes, HEPHL1, FBN2, SULF1, SULF2, and TCN1, were recently discovered in cSCC, which were significantly upregulated compared to normal skin (p < 0.001) and actinic keratosis (AK) (p < 0.01)." (PMID 36980718, 2023).
cholesteatoma (1 paper, 2022). A pathologic process characterized by the proliferation of keratinizing squamous epithelium resulting in the accumulation of keratin and cells in the middle ear and/or mastoid. "However, in our own middle ear expression dataset from the same patients, all 12 genes were DEGs for cholesteatoma: RTN4, RAB5A, CRYBG1, RGS22, HEPHL1, and SPTLC3 were upregulated, while APBB1IP, BHLHE41, ARID3A, C5AR1, CPT1B, and FAM227A were downregulated." (PMID 36699445, 2022).
epilepsy (1 paper, 2023). A brain disorder characterized by episodes of abnormally increased neuronal discharge resulting in transient episodes of sensory or motor neurological dysfunction, or psychic dysfunction. "ACADVL and HEPHL1 appear to have the weakest association with epilepsy and require further studies." (PMID 37645600, 2023).
hair disorders (1 paper, 2019). "Remarkably, complete ablation of Hephl1 in the mouse leads to a curly whisker (vibrissae) hair phenotype, supporting an important role for the ferroxidase activity of HEPHL1 in hair growth and hair disorders." (PMID 31125343, 2019).
vitiligo (1 paper, 2025). Generalized well circumscribed patches of leukoderma that are generally distributed over symmetric body locations and is due to autoimmune destruction of melanocytes. "We identified seven proteins (HEPHL1, PRDX1, DEFA1, CSGALNACT2, HERC4, NDC80, and SPHK2) causally associated with vitiligo risk." (PMID 40856249, 2025).
tumor (1 paper, 2025). "In contrast, Tum_3 tumor cells primarily expressed genes linked to epithelial differentiation and keratinization, such as CNFN, EPS8L1, and HEPHL1." (PMID 40470730, 2025).
HEPHL1 also shares sentences with these, for which no sentence is quoted: Infertility (3 papers); Alzheimer disease (1); attention deficit-hyperactivity disorder (1); breast carcinoma (1); empty follicle syndrome (1); hereditary hypotrichosis simplex (1); otitis media (1); pancreatic agenesis (1); pulmonary fibrosis (1); severe acute respiratory syndrome (1).